GGT6 (gamma-glutamyltransferase 6)
Description:
Hydrolyzes and transfers gamma-glutamyl moieties from glutathione and other gamma-glutamyl compounds to acceptors.
Synonyms: FLJ90165
Tractability: Antibody: UniProt predicts a signal peptide or a membrane-spanning region.
Gene: Protein-coding gene on chromosome 17 (4,556,927 to 4,560,818, reverse strand). Ensembl gene ENSG00000167741.
Subcellular location: Membrane
Subcellular location (Human Protein Atlas): Cytosol
Pathways (Reactome):
Metabolism: Aflatoxin activation and detoxification; Glutathione synthesis and recycling
Drug ADME: Paracetamol ADME
Gene Ontology:
Molecular function: protein binding; glutathione hydrolase activity
Biological process: leukotriene D4 biosynthetic process; glutathione metabolic process
Cellular component: extracellular exosome; membrane
Genetic constraint (gnomAD): Loss-of-function variants: 13 observed, 18.25 expected, observed/expected ratio (o/e) 0.71, 90% interval 0.46 to 1.13. The upper end of that interval is the gene's LOEUF score, 1.13, which puts it in group 4 of 6, group 1 being the genes least tolerant of losing a copy. Missense variants: 619 observed, 607.96 expected, observed/expected ratio (o/e) 1.02, 90% interval 0.95 to 1.09. Synonymous variants: 302 observed, 277.8 expected, observed/expected ratio (o/e) 1.09, 90% interval 0.99 to 1.2.
Homologues: Orthologues: chimpanzee GGT6 (99% identical), macaque GGT6 (94% identical), rabbit GGT6 (77% identical), guinea pig GGT6 (75% identical), pig GGT6 (70% identical), mouse Ggt6 (70% identical), dog GGT6 (70% identical), rat Ggt6 (68% identical), Drosophila melanogaster Ggt-1 (20% identical), Drosophila melanogaster CG4829 (20% identical), Caenorhabditis elegans C53D5.5 (19% identical), Drosophila melanogaster CG1492 (19% identical), and 2 more. Paralogues in human: GGT1 (24% identical), GGT7 (24% identical), GGT5 (22% identical), GGTLC1 (7% identical), GGTLC3 (6% identical), GGTLC2 (6% identical).
Diseases named in the same sentence as GGT6 in open-access papers:
GGT6 is named in the same sentence as 17 diseases in open-access papers, as found by Europe PMC text mining. Sharing a sentence is not in itself a finding about the gene and the disease. The quoted sentences say what the papers report.
head and neck squamous cell carcinoma (2 papers, 2021 to 2025). A squamous cell carcinoma that arises from any of the following anatomic sites: lip and oral cavity, nasal cavity, paranasal sinuses, pharynx, larynx, and salivary glands. "Nonetheless, two recent studies highlighted the prognostic role of GGT6 mRNA in head and neck squamous cell carcinoma and papillary renal cell carcinoma." (PMID 34513707, 2021).
oropharyngeal cancers (1 paper, 2019). Carcinoma, predominantly squamous cell, arising from the epithelial cells of the oropharynx. "A distinct set of prognosticators were identified for HPV+ and HPV- oropharyngeal cancers; ECHDC2, GGT6, HERC5 were showed to be associated with HPV+; HERC5 has a known anti-viral activity and its possible role in HNSCC HPV associated cancer is yet to be studied." (PMID 31310629, 2019).
ovarian carcinoma (1 paper, 2019). A malignant neoplasm originating from the surface ovarian epithelium. "There were two downregulated transcription factors (BARX2 and CDX2), a glutathione regulating enzyme (GGT6) and a serine protease that correlates with improved survival in ovarian cancer (PRSS16)." (PMID 31052165, 2019).
prostate carcinoma (1 paper, 2025). A carcinoma that arises from epithelial cells of the prostate gland. "GGT6 expression exhibited a superb AUC value in prostate cancer diagnosis and was associated with favorable progression-free survival." (PMID 40094020, 2025). "Further analysis in cell culture and xenograft models demonstrated that GGT6 expression was modulated at the transcription level by AR signal activity in prostate cancer." (PMID 40094020, 2025). "Due to a sharp reduction, GGT6 expression exhibited a superb indication for prostate cancer diagnosis." (PMID 40094020, 2025). "Our results showed very strong negative correlations between the expression levels of GGT1/GGT5/GGT6 genes, and their DNA methylation levels in prostate cancer tissues." (PMID 40094020, 2025). "In conclusion, GGT1/GGT5 expression was upregulated but GGT6/GGT7 expression was downregulated in primary prostate cancers." (PMID 40094020, 2025). "In this study, we were the first to report that GGT6 expression was sharply downregulated in primary prostate cancers, which might be due to enhanced promoter DNA methylation." (PMID 40094020, 2025). "ROC analysis indicated GGT6 as a reliable marker for prostate cancer diagnosis (AUC = 0.835)." (PMID 40094020, 2025).
renal cell carcinoma (1 paper, 2019). "Furthermore, female-biased GGT6 has previously been identified as a potential biomarker in renal cell carcinoma, but has not been studied in the context of HCC." (PMID 31615477, 2019).
cancer (6 papers, 2018 to 2025). A tumor composed of atypical neoplastic, often pleomorphic cells that invade other tissues. "Compared to case-matched benign tissues, most cases of cancer tissues expressed higher GGT1/GGT5 genes but lower GGT6/GGT7 genes, of which GGT6 expression showed a dramatic reduction in cancer tissues." (PMID 40094020, 2025). "Our results showed that prostate tissues expressed four major isoforms of GGT family genes (GGT1/5/6/7), of which GGT1 expression was upregulated but GGT6/GGT7 expression was downregulated in cancer tissues compared to benign tissues." (PMID 40094020, 2025). "Among these GGT genes, GGT6 was the only one that exerted a significant upregulation in deceased patients compared to alive ones that were alive, which contrasted with its expression profile in primary cancers with a downregulated expression in cancer tissues." (PMID 40094020, 2025). "Studies related to GGT6 in the field of cancer are very few." (PMID 34513707, 2021). "Further analysis of the model genes within MOCM across pan‐cancer settings revealed that ANLN, CCNB1, CDKN3, EXO1, GJB3 and RAD51AP1 were predominantly overexpressed in tumour tissues, while GGT6 and CYP4B1 were highly expressed in normal tissues." (PMID 38958523, 2024). "Among the top 10 DRGs identified from TCGA-STAD dataset, six are GC related (E2F1, AK1B10, CEBPA, PTK7, RASAL1, GKN), and three are cancer related (DPCR1, GGT6, RAB25)." (PMID 29745833, 2018). "Consistent with GGT6 downregulation and the strong negative correlation, the GGT6 promoter showed a significantly higher methylation level in cancer tissue compared to benign tissues." (PMID 40094020, 2025).
tumor (6 papers, 2014 to 2025). "ROC analysis revealed that GGT6 gene expression exerted a strong factor in distinguishing tumor tissues from benign tissues with an AUC value of 0.835." (PMID 40094020, 2025). "Transcript levels of GGT6 were significantly decreased in the tumor samples compared to the normal tissues (Mann-Whitney, P <0.0001)." (PMID 25472429, 2014). "Subsequent univariate Cox and LASSO regression analyses narrowed the selection to five key genes—GGT6, HAO2, SLPI, MELK, and EIF4A1—whose expression patterns correlated strongly with tumor grade, clinical stage, and metastatic status." (PMID 40709174, 2025).
GGT6 also shares sentences with these, for which no sentence is quoted: glioblastoma (2 papers); papillary renal cell carcinoma (2); renal carcinoma (2); acute kidney injury (1); choroid plexus papilloma (1); gastric cancer (1); hepatocellular carcinoma (1); oral squamous cell carcinoma (1); renal clear cell carcinoma (1); thyroid cancer (1).